CCND2 (cyclin D2)
Diseases named in the same sentence as CCND2 in open-access papers (continued):
Sharing a sentence is not in itself a finding about the gene and the disease.
diabetes (12 papers, 2010 to 2023). "G1/S CDK complexes play a crucial role in beta cell proliferation in mouse and human, and loss of either CDK4 or Cyclin D2 leads to a dramatic loss of beta cell mass and proliferation, resulting in diabetes." (PMID 37407581, 2023). "CCND2, a cell cycle regulator, has also been implicated in the pathobiology of cardiovascular complications related to diabetes, with increased levels related to increased endothelial cell proliferation." (PMID 31899480, 2020). "Our results indicated that cyclin D2 might be involved in the progression of cardiovascular abnormalities associated with diabetes." (PMID 26840039, 2016). "Previous studies have demonstrated that the FOXO/BCL6/cyclin D2 pathway linked to β-cell proliferation and may therefore be considered to be associated with diabetes." (PMID 26308950, 2015). "Downregulation of miR-98 was shown to lead to the upregulation of cyclin D2, which is involved in the vascular complications of type 2 diabetes mellitus, and upregulation of miR-98 prevented cardiac hypertrophy via inhibition of cyclin D2." (PMID 30823517, 2019). "Cyclin D2 is involved in the pathology of vascular complications of type 2 diabetes mellitus (T2DM)." (PMID 26840039, 2016). "These include CCND2, CILP2, PBX4, SH2B3, SLC6A4, TCF7 and KLF14, which have polymorphisms associated with diabetes risk." (PMID 27029739, 2016). "Genetic ablation of Cdk4 activity, cyclin D2, or combined E2f1 and E2f2, results in defective maintenance of adult pancreatic β-cells, eventually resulting in severe diabetes." (PMID 20090907, 2010). "Cyclin D1 partially compensates for the absence of cyclin D2, since the double mutant aggravates this phenotype, with uncontrollable diabetes leading to death at an early age." (PMID 26759123, 2016).
lymphoma (12 papers, 2015 to 2025). A malignant (clonal) proliferation of B- lymphocytes or T- lymphocytes which involves the lymph nodes, bone marrow and/or extranodal sites. "The transcription level of cyclin d3 (Ccnd3) was high, whereas the expression levels of cyclin d1 (Ccnd1) and d2 (Ccnd2) were quite low, presumably reflecting the characteristics of T lymphomas, such as Jurkat cells." (PMID 40734673, 2025). "A genome-wide CRISPR-Cas9 study also demonstrated the importance of CCND2 in the proliferation and survival of adult T-cell leukemia/lymphoma cells." (PMID 37204480, 2023). "BTK is known to enhance cyclin D2 expression that promotes the growth of lymphoma cells." (PMID 37705009, 2023). "An analysis of a representative dataset (Salaverria lymphoma) revealed that MME expression levels were significantly higher in the GCB subtype than those in the ABC subtype and that IL2RA, ETV6, and CCND2 expression levels were higher in the ABC subtype than those in the GCB subtype." (PMID 29992138, 2018). "In contrast, cyclin D2, which is expressed in EBV-transformed LCLs but not in EBV+ BLs, is turned down in the ΔEBNA2 + Myc lymphomas." (PMID 38620028, 2024).
breast tumor (11 papers, 2004 to 2019). "Although cyclins are generally considered as positive mediators of mitogen-induced cell cycle progression, it has been shown that loss of CCND2 expression occurs in primary breast tumours." (PMID 14710226, 2004). "As compared with paired normal tissues and healthy individuals, CCND2 promoter hypermethylation was detected in 40.9% of breast tumors and 44.4% of plasma circulating cell-free DNA of patients." (PMID 30308939, 2018). "To evaluate epigenetic differences in tumor-related genes relating to ER and HER2/neu status of primary tumors, we examined the promoter methylation status of the promoter region CpG islands of eight major breast tumor-related genes (RASSF1A, CCND2, GSPT1, TWIST, APC, NES1, RARβ2, and CDH1)." (PMID 18485221, 2008).
myocardial infarction (11 papers, 2021 to 2025). Gross necrosis of the myocardium, as a result of interruption of the blood supply to the area, as in coronary thrombosis. "Beyond its implications in cancer, studies in animal models have demonstrated that CCND2 can activate the cell cycle in myocardial cells following myocardial infarction in mice and pigs, indicating its role in myocardial cell development." (PMID 40487928, 2025). "In mouse and porcine models of myocardial infarction, up-regulation of CCND2 expression promotes cardiomyocyte proliferation, reduces myocardial infarct area, and improves cardiac performance." (PMID 39421829, 2024). "Myocardial infarction was induced in adult immunodeficient mice, followed by intramyocardial injection of hiPSC-CMs expressing either CCND2/channelrhodopsin 2 (hiPSC-CCND2OE/ChR2OECMs) or CCND2/luciferase (hiPSC-CCND2OE/LuciOECMs)." (PMID 35326403, 2022). "Previous studies have shown that the overexpression of cyclin D2 and cyclin A2 in the hearts of rats with myocardial infarction can induce cardiomyocyte proliferation and facilitate the repair of scarred areas following myocardial infarction." (PMID 39080192, 2024). "Previous studies successfully demonstrated that transgenic models expressing Cyclin D2 under the transcriptional regulation of the alpha-cardiac myosin heavy chain (MHC) promoter showed a better recovery after Myocardial Infarction (MI), with an increase in the number of living cardiomyocytes." (PMID 36120584, 2022). "Overexpression of cell cycle-related gene regulators, such as Cyclin A2, Cyclin D1, and Cyclin D2, could enhance CM cell cycle activity and improve repair following myocardial infarction (MI) 4-6." (PMID 34646377, 2021). "Landmark studies by Zhang’s group showed that cyclin D2 (CCND2) overexpression activated cell cycle progression in hiPSC-CMs and that transplanting these CCND2-overexpressing hiPSC-CMs into mouse or swine hearts with myocardial infarction significantly enhanced myocardial repair." (PMID 37649113, 2023).
hepatocellular carcinoma (10 papers, 2010 to 2025). A malignant tumor that arises from hepatocytes. "CCND2 hypermethylation, and, therefore, low CCND2 protein expression are associated with a poor prognosis in epithelial ovarian cell cancer and hepatocellular carcinoma recurrence." (PMID 30308939, 2018). "Canagliflozin-treated HepG2 cells demonstrated increased expression of the cell growth regulator hepatocyte nuclear factor 4 (HNF4), with a reduced expression of cyclin D1, cyclin D2, and cdk4, resulting in cell cycle arrest in a hepatocellular carcinoma (HCC) cell line." (PMID 40869400, 2025). "It is known that a variety of cell cycle proteins play a key role in hepatocellular carcinoma, such as Cyclin D1 (CCND1), C-myc or Ras, cyclin D2 (CCND2), etc.." (PMID 37400985, 2023). "Furthermore, reduced expression of cyclin D1, cyclin D2 and cdk4 leading to cell cycle arrest in a hepatocellular carcinoma (HCC) cell line have been reported after treatment with canagliflozin." (PMID 35328527, 2022).
medulloblastoma (10 papers, 2010 to 2023). A malignant, invasive embryonal neoplasm arising from the cerebellum. "The decrease in the expression levels of proliferation-related targets of miR-193a like E2F1, CCND1, and several other cell cycle regulators like CDK2, CCND2 is consistent with the growth inhibition of medulloblastoma cells upon the expression of miR-193a." (PMID 32410663, 2020). "In our study, eight genetic variants, annotating three genes involved in the sonic hedgehog signaling pathway (CCND2, PTCH1, and GLI2), were indicted as associated with medulloblastoma risk." (PMID 26290144, 2015). "Eight genetic variants annotating three genes in the sonic hedgehog signaling pathway; CCND2, PTCH1, and GLI2, were found to be associated with the risk of medulloblastoma (Pcombined < 0.05)." (PMID 26290144, 2015). "We evaluated Cyclin D2 expression in 6 cell lines and 14 medulloblastoma tumor samples and observed that most of them showed high expression levels of Cyclin D2, with the exception of cell line SK-PN-DW and one tumor sample." (PMID 21059263, 2010). "Exploration of epigenetic regulation of Cyclin D2 in medulloblastomas and astrocytomas was motivated by previous studies which had revealed Cyclin D2 silencing in cancers such as breast, lung, and prostate, due to promoter hypermethylation." (PMID 21059263, 2010). "To complete this study, we determined the expression of Cyclin D2 in 6 medulloblastoma cell lines and 14 tumor samples, and overall, we observed high expression levels of Cyclin D2 that correlated with high levels of GLI1 expression." (PMID 21059263, 2010). "GLI1 appears to up-regulate PTCH1 expression in both medulloblastomas and astrocytomas, and remaining genes tested, namely, Cyclin D2, Plakoglobin, PAX6, and NKX2.2, only in medulloblastomas." (PMID 21059263, 2010). "Analysis of promoter methylation suggests that epigenetic regulation of Cyclin D2 is stronger in astrocytomas than in medulloblastomas, while epigenetic regulation of PTCH1 is weak in both tumors." (PMID 21059263, 2010). "To determine whether GLI1 regulates Cyclin D2 in medulloblastomas, we quantified levels of Cyclin D2 transcript upon silencing of GLI1 by siRNA in the Daoy medulloblastoma cell line." (PMID 21059263, 2010). "Whereas the medulloblastoma cells were irradiated, a YAP high expression was detected, which induced the cell proliferation through high-rise Cyclin D2 (CCND2), and phosphorylated H3 promoted the tumor aggressiveness and tumor recurrence." (PMID 34900673, 2021). "To further our understanding of epigenetic regulation, we also monitored the methylation status of the Cyclin D2 and PTCH1 promoters in 14 cell lines and 58 tumor samples derived from medulloblastomas and astrocytomas." (PMID 21059263, 2010). "In the course of our studies, we sought to understand the regulation of certain downstream target genes of the Shh pathway, including PTCH1, Cyclin D2, Plakoglobin, NKX2.2, and PAX6, in a panel of medulloblastoma and astrocytoma cell lines and tumors." (PMID 21059263, 2010). "In this study, we sought to understand the regulatory roles of GLI1, the immediate downstream activator of the Shh signaling pathway on its downstream target genes PTCH1, Cyclin D2, Plakoglobin, NKX2.2 and PAX6 in medulloblastoma and astrocytic tumors." (PMID 21059263, 2010). "PTCH1 promoter methylation was less frequently observed than Cyclin D2 promoter methylation in astrocytomas, and not at all in medulloblastomas." (PMID 21059263, 2010). "We also observed methylation of the cyclin D2 promoter in a significant number of astrocytoma cell lines (63%) and primary astrocytoma tumor samples (32%), but not at all in any medulloblastoma samples." (PMID 21059263, 2010). "We did not observe any changes in the pattern of Cyclin D2 expression upon treatment of the medulloblastoma cell lines with 5-Aza-2'-deoxycytidine and TSA." (PMID 21059263, 2010).
medulloblastoma (continued). "However, high levels of GLI1 correlated with high levels of Cyclin D2 and PTCH1 in medulloblastoma cell lines and tumor samples." (PMID 21059263, 2010). "In our study, we have silenced expression of GLI1 using a small interfering RNA (siRNA), followed by the determination of gene expression patterns of PTCH1, Cyclin D2, Plakoglobin, NKX2.2 and PAX6 in 14 cell lines and 41 primary medulloblastoma and astrocytoma tumor samples." (PMID 21059263, 2010). "Our study revealed, to a certain extent, hypermethylation of the Cyclin D2 promoter, although methylation did not fully correlate with silencing of expression in medulloblastoma cell lines." (PMID 21059263, 2010). "In medulloblastoma samples, no methylation was detected by MCA-Meth primers, even though some tumors expressed Cyclin D2 at low levels." (PMID 21059263, 2010).
acute myeloid leukemia (9 papers, 2018 to 2025). Acute myeloid leukemia (AML) is a group of neoplasms arising from precursor cells committed to the myeloid cell-line differentiation. "Thr280Ala-mutated CCND2 leads to the increased the phosphorylation of retinoblastoma protein, thereby causing significant cell cycle changes and increased proliferation of acute myeloid leukemia cell lines." (PMID 30308939, 2018). "RUNX1 is an oncogenic transcription factor and a recognized driver mutation in acute myeloid leukemia (AML), where it plays a key role in regulating CCND2 expression." (PMID 40508126, 2025). "In our previous studies, we demonstrated that isoflavonoid 8-hydroxydaidzein induced apoptosis by downregulating acute myeloid leukemia (AML)-associated genes such as RUNX1, CCND2, and MYC in U937 cells while upregulating CDKN1A (p21) and suppressing BCL2 expression in K562 cells." (PMID 40508126, 2025). "Cyclin D2 (CCND2) is a key regulator of the G1/S transition and plays an important role in cell cycle progression and the pathogenesis of acute myeloid leukemia (AML)." (PMID 40508126, 2025). "Pyzer AR and colleagues reported that c-myc can promote MDSC proliferation by upregulating cyclin D2 and E1 in acute myeloid leukemia (AML)." (PMID 30925926, 2019). "In acute myeloid leukemia (AML), ADAR1 promotes tumor cell proliferation by regulating key molecules in the Wnt pathway (such as β-catenin, c-Myc, and Cyclin D2)." (PMID 41488000, 2025). "Cyclin D2 has critical roles in B cell activation and also has been shown to be positively regulated by the RUNX1-ETO fusion oncoprotein in acute myeloid leukemia." (PMID 34810221, 2021). "Similar results were obtained using human BM-MSCs in coculture with chronic myeloid leukemia (CML), acute myeloid leukemia (AML) and T-ALL cell lines, showing significantly reduced cyclin D2 activity and subsequent G1 phase blockade." (PMID 33383723, 2020).
cardiac hypertrophy (9 papers, 2015 to 2025). "OGN modulates myocardial hypertrophy through various molecular mechanisms, including the hyperglycemia-induced upregulation of ERK1/2 and cyclin D2." (PMID 39861172, 2025). "More specifically, several lines of evidence derived from our studies support that miR-16 inhibits cardiac hypertrophy through targeting CCND1, CCND2 and CCNE1." (PMID 25583328, 2015). "We have provided further evidence to support that miR-16 inhibited cardiac hypertrophy through targeting CCND1, CCND2, CCNE1 and cyclin/Rb pathway." (PMID 25583328, 2015). "In this study, we have shown that down-regulation of miR-16 was accompanied by up-regulations of CCND1, CCND2 and CCNE1 in hypertrophic myocardium and cell models of cardiac hypertrophy." (PMID 25583328, 2015). "Histone acetylation is involved in regulating cardiac transcription factors, for example, O-GlcNAcylation is important in hyperglycemia-induced cardiac hypertrophy through ERK1/2 and cyclin D2." (PMID 26418041, 2015). "Therefore, this study demonstrates that increased expression of CCND1, CCND2 and CCNE1 were modulated at both transcriptional level and post-transcriptional level during cardiac hypertrophy." (PMID 25583328, 2015). "Notably, our findings showing that down-regulation of miR-16 results in cardiac hypertrophy through up-regulating the expressions of CCND1, CCND2 and CCNE1 have raised many other questions." (PMID 25583328, 2015).
microcephaly (9 papers, 2015 to 2025). A congenital or acquired developmental disorder in which the circumference of the head is smaller than normal for the person's age and sex. "With LOF mutations in the CDK4/6 binding partner CCND2 causing microcephaly, and GOF CCND2 mutations leading to brain overgrowth, we conclude that CDK4 and G1 Cyclin–CDK activity represents a key axis controlling human brain growth." (PMID 40210435, 2025). "Recently, loss-of-function CCND2 variants resulting in protein truncation were found in patients with microcephaly, the inverse brain phenotype to MPPH." (PMID 37510349, 2023). "Putative CCND2 loss of function variants have been previously reported as a strong microcephaly candidate gene in four unrelated patients." (PMID 37501076, 2023). "This is the third reported association between loss of function CCND2 variant and microcephaly, to our knowledge." (PMID 37501076, 2023). "We confirmed that loss of function variants in CCND2 associated with microcephaly, short stature, and developmental delay." (PMID 37501076, 2023). "The opposite phenotypes produced by CDK6 loss-of-function and cyclin D2 gain-of-function mutations (microcephaly vs megalencephaly, respectively) are remarkably predictable considering that the two proteins heterodimerize to produce an active protein kinase." (PMID 32762766, 2020). "Additionally, CCND2 has been implicated in human brain growth, with mutations in this gene associated with conditions such as microcephaly and dwarfism." (PMID 40487928, 2025). "Prior to this study, the effect of loss-of-function mutations on CCND2 was poorly understood, with only mice studies indicating that Ccnd2-KO causes a lack of cerebellar stellate interneurons, supressed adult hippocampal neurogenesis, and severe microcephaly." (PMID 37510349, 2023). "Another example is cyclin D2, whose role in neuronal development has been identified and whose mouse knockout models show a loss of cortical intermediate progenitor cells, laminar thinning and microcephaly, in congruence with the megalencephaly caused by gain-of-function mutations in humans." (PMID 32762766, 2020). "CDK4 and most CCND2 microcephaly individuals display similar growth restriction, with reduced growth parameters at birth of −1 to −2 SD but more significant microcephaly postnatally, suggestive of a prenatal-onset origin with a delayed presentation." (PMID 40210435, 2025). "Loss of either cD2 or cD1 in mouse results in smaller forebrains (microcephaly), but only Ccnd2 null mice (cD2−/−) show selectively affected specific neuronal subtypes." (PMID 33613193, 2021). "Notably, heterozygous frameshift and nonsense variants in CCND2 (encoding Cyclin D2), the partner of CDK4/6 with major roles in neural progenitor proliferation, also result in microcephaly." (PMID 40210435, 2025). "Whereas cyclin-D2 can compensate for cyclin-D1 deficiency in the VZ, the basal progenitor population in the SVZ shows a cyclin-D2 dependence for proliferation, and the corresponding knock-out model results in microcephaly." (PMID 24859217, 2015). "We observed one single m6A site near the stop codon in 7 microcephaly-related E-SMRs, including Brca2, Cep152, Ddx11, Nde1, Kif14, Stil and Cdk5rap2, 3 polymicrogyria-related E-SMRs (Eomes/Tbr2, Pax6 and Foxp2), and 3 megalencephaly-related E-SMRs (Gli3, Ccnd2 and Kif7)." (PMID 32992647, 2020). "NARS1 mutations affected gene expression in pathways related to cell cycle (CCND2) and proliferation (KI67), likely contributing to microcephaly." (PMID 32788587, 2020).
non-small cell lung carcinoma (9 papers, 2014 to 2022). A group of at least three distinct histological types of lung cancer, including non-small cell squamous cell carcinoma, adenocarcinoma, and large cell carcinoma. "A recent study reported that reduced expression of CCND2 in stage III non-small cell lung cancer (NSCLC) is associated with poor recurrence-free survival." (PMID 24980822, 2014). "For example, hsa-miR-1248 was reported to bind with cyclin D2 and tumor-promoting gene tripartite motif-containing protein 24 to regulate the progression of non-small cell lung cancer (NSCLC)." (PMID 36028821, 2022). "miR-146a-5p acts as an oncosuppressor in non-small-cell lung cancer, inhibiting tumor cell proliferation by direct targeting of cyclin D1 and cyclin D2." (PMID 30611259, 2019). "Circular RNA circ-RAD23B promotes cell growth and invasion by targeting miR-593-3p/CCND2 and miR-653-5p/TIAM1 pathways in non-small cell lung cancer." (PMID 32228518, 2020). "MiR-646 is involved in inhibiting proliferation and metastasis of non-small cell lung cancer by binding to FGF2 and CCND2." (PMID 32669977, 2020).